EGFR (epidermal growth factor receptor)
Diseases named in the same sentence as EGFR in open-access papers (continued):
Sharing a sentence is not in itself a finding about the gene and the disease.
breast carcinoma (continued). "Therefore, we investigated the presence of EGFR-mutations in 131 norwegian patients diagnosed with early breast cancer using real-time PCR methods." (PMID 26267891, 2015). "ER-α36 also increases Epidermal Growth Factor Receptor (EGFR) expression and decreases ERα expression, which could be an underlying mechanism for acquired tamoxifen resistance in breast cancer." (PMID 26396174, 2015). "However, an increasing body of evidence suggests significant worldwide variation in somatic EGFR mutations in breast cancer patients." (PMID 26267891, 2015). "It downregulated EGFR and p-EGFR levels in MCF-7 cells, reduced the phosphorylation of EGFR in MDA-MB-231 (ER−/PR−/HER2−/EGFR+) breast cancer cells and interrupted the association between α6β4 integrin and EGFR by blocking the distribution α6β4 integrin into lipid rafts." (PMID 26694341, 2015). "We wanted to know whether the high expression of EGFR in the breast cancer cells or tissues is associated with the high level of KLF8." (PMID 26025929, 2015). "Additionally, modulation of PCNA and Cdc2 stability and activity through their association with nuclear EGFR contributes to uncontrolled proliferation and DNA repair in breast cancer cells." (PMID 25997448, 2015). "There may be a special role for HER2 (EGFR) as molecule associated with CD24 which together with phosphorylated Akt promotes breast cancer cell survival." (PMID 26626416, 2015). "In addition, we analysed the expression of genes associated, in human and pet mammary cancers, with stem/progenitor cell survival, self-renewal and tumor aggressiveness, such as EGFR, ER-α and CXCR4." (PMID 25884842, 2015). "Interestingly, ETR breast cancer cells express high levels of EGFR and other growth factor receptors that have been linked to normal breast stem cells." (PMID 24919951, 2014). "EGF induced the associations of Gi3α with p-EGFR, Gab1 and Shp2 in breast cancer cells." (PMID 24521094, 2014). "EGFR/MET complex associated with SRC were reported in EGFR TKI-resistant breast cancer cells." (PMID 24714091, 2014). "We found that down regulation of CXCR7 decreased the level of activation of phospho-EGFR and phosho-ERK1/2, which suggests a strong association of CXCR7 with EGFR in breast cancer in accordance with our in situ co-IP data and confirms a role of CXCR7 in EGFR mediated ERK signaling." (PMID 25168820, 2014). "Epidermal growth factor receptor overexpression, or constitutive activation, has been implicated in the progression of a variety of cancers including lung, head and neck, colon, brain, and breast cancer by promoting tumor angiogenesis and metastasis." (PMID 25566499, 2014). "The data suggest that the presence of the variant forms of EGFR polymorphisms may lead to better prognosis in breast cancer, especially in patients with luminal A tumors." (PMID 24629097, 2014). "We hypothesized that two EGFR functional polymorphisms, a (CA)n repeat in intron 1, and a single nucleotide polymorphism, R497K, may affect EGFR expression and breast cancer clinical profile." (PMID 24629097, 2014). "The occurrence of the EGFR mutation and its correlation with the appearance and/or the subcellular localization of Y845 phosphorylation have been examined in NSCLCs, adenocarcinomas, and breast cancer." (PMID 23702846, 2013). "Dicer positivity was also associated with expression of basal-like biomarker EGFR and, in the analysis of breast cancer subtypes, luminal A subtype showed a significantly lower proportion of Dicer positive patients than basal-like and HER2 overexpressing subtypes." (PMID 24386264, 2013). "Thus, we identified seven 1q candidate genes strongly associated with the poor survival of breast cancer patients and identified the possibility of targeting them with EGFR/RAS/PI3K inhibitors." (PMID 24147022, 2013).
breast carcinoma (continued). "Interestingly, it was recently reported that paracrine EGFR signaling between tumor-associated macrophages and murine breast cancer cells can promote a cancer stem cell-like phenotype." (PMID 24156623, 2013). "The expression of epidermal growth factor receptor (EGFR) in basal-like breast cancer is associated with poor prognosis but more importantly, it provides the possibility to therapeutically target the receptor using either tyrosine kinase inhibitors (TKIs) or therapeutic monoclonal antibodies." (PMID 24354805, 2013). "Interestingly, nuclear Kaiso was also abundant in BRCA1-associated breast cancer (p<0.001) and invasive breast cancer overexpressing EGFR (p = 0.019)." (PMID 22662240, 2012). "Vimentin expression in breast carcinomas may have an association with poor prognosis, hormone receptor negativity and co-expression of EGFR, which are consistent features for basal-like tumors." (PMID 23082819, 2012). "It has been reported that co-expression of EGFR and c-Src in breast cancer cell lines results in their association and c-Src-mediated phosphorylation of the EGFR at tyrosine 845 (Tyr845) within its catalytic domain, which contributes to enhanced cell proliferation and tumor formation in vivo." (PMID 22927910, 2012). "Recently we reported that insulin receptor substrate 1 (IRS-1), classically an adaptor protein for the insulin-like growth factor type I receptor (IGF-IR), associates with the epidermal growth factor receptor in oestrogen receptor (ER)-positive (ER+) tamoxifen-resistant breast cancer cells." (PMID 21939528, 2011). "Breast cancers which demonstrate EGFR protein expression, gene amplification and/or gene mutations may benefit therapeutically from tyrosine kinase inhibitors." (PMID 21702909, 2011). "Overexpression of EGFR and versican has been reported in association with breast cancers." (PMID 22096483, 2011). "The expression of EGFR in breast cancer has been linked to endocrine resistance and poor outcomes." (PMID 21396117, 2011). "In addition, EGFR-mediated phosphorylation of MUC1-C in breast cancer cells was associated with decreases in PKM2 activity." (PMID 22140559, 2011). "In breast cancer, EGFR and HER2 are frequently over-expressed and are associated with aggressive clinical behavior and poor outcome; however, the outcome for patients with these highly aggressive tumors has markedly improved with the development of anti-HER2 therapies." (PMID 21050422, 2010). "Furthermore, tyrosine kinase membrane receptors are also mutated or activated (ie: ErbB2, EGFR) contributing to AKT deregulation in mammary tumors." (PMID 20174572, 2010). "EGFR seems to be particularly associated with basal type breast cancers and also may be a marker of the epithelial to mesenchymal transition often found in CTCs." (PMID 19500345, 2009). "Interaction of Src with numerous breast cancer-associated growth factors and signalling pathways, such as prolactin, EGFR, ERK1/2, PI3-kinase, and oestrogen receptor, supports the notion that Src activity contributes to the growth and survival of breast cancer cells." (PMID 19513066, 2009). "This article reports our attempt to subclassify male breast carcinomas based on the immunoprofile, and to evaluate the association of the subtypes with histologic type, nuclear grade, lymph node status, clinical stage, and expression of EGFR and NF-κB." (PMID 19442295, 2009).
breast carcinoma (continued). "EGFR is reported to be expressed in 14% to 91% of patients with breast cancer, and in several studies it has also been associated with poor prognosis, although its prognostic value remains unclear." (PMID 18522728, 2008). "EGFR expression has also been linked to activation of ErbB2 in human breast cancers." (PMID 18320059, 2008). "In addition, the length of this polymorphism has been observed to correlate inversely with EGFR transcription in both in vitro experiments and breast cancer specimens." (PMID 18664296, 2008). "In conclusion, the present study suggests that EGFR as well as HER2 mRNA overexpression are prognostic factors of worse clinical outcome in high-risk operable breast cancer patients, whereas HER3 and HER4 mRNA overexpression are both associated with a better prognosis." (PMID 18985033, 2008). "Alternatively, this finding may be accounted for by the strong association between EGFR expression and loss of differentiation in breast cancer." (PMID 18522728, 2008). "The EGFR is expressed in 15–35% of breast cancers, and is also associated with a poor prognosis." (PMID 16622439, 2006). "In addition, p21 expression can indeed be up-regulated by epidermal growth factor receptor and transforming growth factor β1 which are associated with higher tumor grade and disease progression in breast carcinoma." (PMID 16869981, 2006). "Similarly, of the seven sporadic breast cancers with somatic EGFR mutations, four (57.1%) had mutations only in the stroma." (PMID 15841079, 2005). "Interestingly, the phosphorylated EGFR was predominantly in the nuclei, which was in strong agreement as other studies, suggested that the nuclear EGFR positively associated with poor survival outcomes in patients with breast cancer." (PMID 16288304, 2005). "Thus, the frequency of EGFR mutations was significantly higher in BRCA1/2-related breast cancers compared to that in sporadic ones (P=0.0079)." (PMID 15841079, 2005). "The association of RON with MET and EGFR has been investigated by immunoprecipitation and cross-linking experiments, demonstrating receptor transphosphorylation, which may play a role in predicting therapeutic response and drug resistance in breast cancer." (PMID 40560045, 2025). "Examination of the protein–protein interaction networks suggested that the correlation of TGFB2-related markers could potentially complement the PAM50 signature in the assessment of OS prognosis in breast cancer patients following validation of the TGFB2/EGFR/MYC protein associations in tumors." (PMID 41373732, 2025). "Specifically, when detecting epidermal growth factor receptor (EGFR) gene mutations in breast cancer, ddPCR was capable of identifying mutations with an abundance as low as 0.1%, whereas qPCR could only detect mutations at a minimum abundance of 1% in plasmids." (PMID 40042093, 2025). "Together, these findings suggest that CEACAM5 expression and its serum surrogate marker, CEA, may serve as subtype‐specific prognostic or predictive biomarkers in both lung and breast cancers, particularly in tumors driven by EGFR mutations or enriched in luminal and HER2‐related signaling pathways." (PMID 40856433, 2025). "However, mutations in EGFR enhance antiapoptotic signaling and cause excess cell proliferation and may result in early metastasis in lung and breast cancer patients." (PMID 38731403, 2024). "In breast cancer, its overexpression may be associated with longer OS and progression-free survival, which may take part in cell cycle regulation, and may be related to the EGFR/Akt signaling pathway." (PMID 37214471, 2023).
breast carcinoma (continued). "Therefore, miR-133a may act as a tumor suppressor through inhibition of the EGFR-AKT axis in breast cancers with EGFR expression, which is a hallmark of QNBC." (PMID 35203574, 2022). "Within the ER- cohort, HER2low breast cancer was significantly associated with increased regional nodal positivity, lower density of TILs and a lower expression of Ki-67 and epidermal growth factor receptor (EGFR) compared to HER2- cases (P < 0.001, P = 0.034, P = 0.031 and P = 0.046 respectively)." (PMID 35902644, 2022). "Since breast cancer progression is closely linked to EGFR tyrosine kinase signal; it can be speculated that diosgenin-mediated Rap1 signal could attenuate tumor invasion and metastasis; was observed to be modulated via the modulation of three genes i.e., PDGFRB, IGF1R, and FGFR2." (PMID 36686654, 2022). "Therefore, EGFR mutation may provide clues of a common etiological pathway between primary lung adenocarcinoma and breast cancer." (PMID 36313724, 2022). "As HER2, DDR1/2, and EGFR are associated with metastasis of breast cancer, one could assume that the enhanced activity of these receptor tyrosine kinases mediates the enhanced migration, invasion, chemotaxis, and metastasis to bone in the AKT3 knockdown 231-BO cells." (PMID 33670586, 2021). "Two types of pathological alterations of EGFR in cancers, the kinase-activating mutation in EGFR and the overexpression of the EGFR protein, are common traits in many solid tumors and validated delivery targets for several cancers including lung, colorectal, and certain subtypes of breast cancer." (PMID 33981532, 2021). "Indeed, in breast cancer patients increasing ctDNA levels are associated with inferior survival and increased risk of recurrence, while one study reported 96% of EGFR-mutated colorectal or NSCLCs demonstrated a reduction in ctDNA plasma levels after initiation of targeted therapy." (PMID 33192972, 2020). "Certain cancer types with favorable prognostic factors, such as lung adenocarcinoma with tyrosine kinase inhibitor (TKI)-sensitive epidermal growth factor receptor (EGFR) mutation or hormone receptor-positive breast cancer, may achieve long-term survival once they survived the CPR events." (PMID 31263137, 2019). "However, therapeutic resistance may arise through loss of ER expression, mutations in ER or overexpression of alternative breast cancer-driving pathways such as ERBB1/EGFR." (PMID 32039208, 2019). "In breast cancer this mainly occurs via mutations resulting in overexpression of hormone receptors including the estrogen receptor (ER), androgen receptor (AR), epidermal growth factor receptor (EGFR), human epidermal growth factor receptor 2 (HER2) and their corresponding ligands." (PMID 31666932, 2019). "Given that we observed focal loss of PTEN in normal human breast tissue, our findings indicate that a percentage of patients with stromal loss of PTEN might be at risk for subsequent breast cancer via epithelial EGFR/ErbB2 activation and subsequent genomic instability." (PMID 30018330, 2018). "The observation that silencing of IKKε in epithelial breast cancer cells significantly diminishes EGFR expression levels, suggest that the association between IKKε and EGFR might result at least in part from EGFR expression levels being placed under the control of IKKε-dependent signalling." (PMID 28532474, 2017). "Therefore, in clinical settings, EGFR inhibitors have been efficacious for the treatment of tumors associated with EGFR overexpression: lapatinib, an inhibitor of the kinase domain of EGFR, is used for metastatic breast cancers in conjunction with conventional cytotoxic drugs." (PMID 29291022, 2017). "Consequently, breast cancer tumors overexpressing EGFR might be associated with unfavorable survival outcomes." (PMID 27055285, 2016).
breast carcinoma (continued). "In addition, overexpression of p110β blocks the EGF-induced migration in breast cancer cells, suggesting abundant p110β may replace p110α to interact with EGFR and results in deficiency of active p110α." (PMID 27176481, 2016). "Interestingly, the ATXN2 gene has been found to be altered by copy number, mutation or expression in ~9% of breast cancers in the TCGA dataset and this may be another mechanism for tumour cells to potentiate EGFR signalling." (PMID 25969993, 2015). "In breast cancer, the loss of miR-133a expression has been associated with poor survival, and restoration of this expression was found to reduce cell invasion in breast cancer cell-lines and also regulate proliferation by targeting epidermal growth factor receptor." (PMID 25104873, 2014). "However, maybe just as in breast cancer, EGFR mutation or amplification were rare events and membranous staining pattern of EGFR might be the best way to decide eligibility for anti-EGFR therapy, target therapy was valuable in NSCD10s." (PMID 23356903, 2013). "Interestingly, Arf1 has also been implicated in recruitment of p85 subunits of PI3K to EGFR in breast cancer cells, providing an additional possible mechanism by which VAPB could regulate AKT activities." (PMID 23049696, 2012). "However, in this study, EGFR gene mutations could be identified in only 2 out of 139 cases (1.4%) of the breast carcinoma samples, confirming that EGFR gene mutations are rare in Chinese patients." (PMID 22132735, 2011). "This study aimed to classify the molecular subtypes of male breast cancers based on the expression profile of immunomarkers and to evaluate their association with clinicopathological features and expression patterns of epidermal growth factor receptor (EGFR) and nuclear factor κB (NF-κB)." (PMID 19442295, 2009). "Given our and other existing data on the tumour microenvironment, it may be postulated that the high frequencies of stromal EGFR mutations in sporadic and hereditary breast cancers could confound responsiveness to EGFR-TKI and may help explain interpatient variation." (PMID 15841079, 2005). "Thus, loss of bcl-2 expression in breast cancer is associated with a range of molecular markers of poor prognosis and may define part of an ER-negative, EGFR-positive phenotype." (PMID 8286195, 1994). "Our clinical data showed a significant correlation between antiestrogen treatment for breast cancer and mutant EGFR expression (p = 0.021) in lung adenocarcinoma patients." (PMID 41597172, 2026). "Together, these findings reveal a role for the TGF-α/EGFR axis in lymph metastasis and propose a rationale for repositioning EGFR-targeted therapies toward targeting early metastatic spread and immunomodulation in breast cancer." (PMID 41932901, 2026). "Epidermal growth factor receptor (EGFR) and albumin-based systems have emerged as key platforms for targeted and efficient drug delivery in breast cancer therapy, particularly for TNBC, which lacks classical hormonal and HER2 targets." (PMID 41489768, 2026). "This study identified that EGFR amplification occurs in ~1–5% of breast cancer patients with shorter overall survival compared to unamplified patients." (PMID 41291067, 2026). "In a murine breast cancer model, EGFR knockout exhibited minimal impact on primary tumor growth but significantly suppressed metastasis, supporting the clinical association between high EGFR expression and poor prognosis." (PMID 42190815, 2026). "Both the in vitro and in vivo results indicate that PPEA-polyplexes have the potential to inhibit the growth of tumors which over-express the EGFR, including colon and breast cancer cells." (PMID 42085373, 2026). "Despite their promise, thiazine derivatives remain underexplored as EGFR inhibitors for breast cancer." (PMID 41552637, 2026). "EpCAM, HER2, and EGFR are the most commonly used surface markers for breast cancer CTCs and form a good foundation for the detection of CTCs." (PMID 41543394, 2026).